LGALS3 (galectin 3)
Description:
Galactose-specific lectin which binds IgE. May mediate with the alpha-3, beta-1 integrin the stimulation by CSPG4 of endothelial cells migration. Together with DMBT1, required for terminal differentiation of columnar epithelial cells during early embryogenesis (By similarity). In the nucleus: acts as a pre-mRNA splicing factor. Involved in acute inflammatory responses including neutrophil activation and adhesion, chemoattraction of monocytes macrophages, opsonization of apoptotic neutrophils, and activation of mast cells. Together with TRIM16, coordinates the recognition of membrane damage with mobilization of the core autophagy regulators ATG16L1 and BECN1 in response to damaged endomembranes.
Synonyms: GALBP; MAC2; MAC-2; GALIG; CBP35; GAL3; L31; LGALS2
Tractability: Small molecule: a drug acting on it is in phase 2 or 3 trials; a structure with a bound ligand is known; a high-quality ligand is known. Antibody: UniProt places it where antibodies can reach, with high confidence; its Gene Ontology location is reachable by antibodies, with high confidence. PROTAC: ubiquitination databases record sites on it; its protein half-life has been measured; a small molecule that binds it is known. Other modalities: a drug acting on it is in phase 2 or 3 trials.
Target class: Other cytosolic protein
Safety:
Unwanted effects reported when the protein is acted on. In parentheses: how it was acted on, where the effect was seen, and who reports it.
an immediate reaction to beta-lactam antibiotics (source: ClinPGx)
Gene: Protein-coding gene on chromosome 14 (55,121,352 to 55,148,022, forward strand). Ensembl gene ENSG00000131981.
Subcellular location: Cytoplasm; Nucleus; Secreted
Subcellular location (Human Protein Atlas): Cytosol; Nucleoplasm; Plasma membrane; Predicted to be secreted
Pathways (Reactome):
Gene expression (Transcription): RUNX1 regulates transcription of genes involved in differentiation of myeloid cells; RUNX2 regulates genes involved in differentiation of myeloid cells
Immune System: Advanced glycosylation endproduct receptor signaling; Neutrophil degranulation
Gene Ontology:
Molecular function: carbohydrate binding; chemoattractant activity; IgE binding; laminin binding; molecular condensate scaffold activity; protein binding; protein phosphatase binding; protein phosphatase inhibitor activity; receptor ligand inhibitor activity; RNA binding; disaccharide binding; receptor ligand activity
Biological process: eosinophil chemotaxis; epithelial cell differentiation; macrophage chemotaxis; monocyte chemotaxis; mononuclear cell migration; negative regulation of endocytosis; negative regulation of extrinsic apoptotic signaling pathway; negative regulation of NK T cell activation; neutrophil chemotaxis; positive chemotaxis; positive regulation of calcium ion import; positive regulation of dendritic cell differentiation; positive regulation of mononuclear cell migration; positive regulation of protein localization to plasma membrane; positive regulation of protein-containing complex assembly; regulation of extrinsic apoptotic signaling pathway via death domain receptors; regulation of T cell apoptotic process; regulation of T cell proliferation; negative regulation of immunological synapse formation; negative regulation of T cell activation via T cell receptor contact with antigen bound to MHC molecule on antigen presenting cell; negative regulation of T cell receptor signaling pathway; negative regulation of alpha-beta T cell activation; signal transduction
Cellular component: cytoplasm; cytosol; extracellular exosome; extracellular matrix; extracellular region; immunological synapse; membrane; mitochondrial inner membrane; nucleoplasm; nucleus; cell surface; ficolin-1-rich granule membrane; plasma membrane; secretory granule membrane
Genetic constraint (gnomAD): Loss-of-function variants: 14 observed, 19 expected, observed/expected ratio (o/e) 0.74, 90% interval 0.49 to 1.15. The upper end of that interval is the gene's LOEUF score, 1.15, which puts it in group 5 of 6, group 1 being the genes least tolerant of losing a copy. Missense variants: 261 observed, 271.11 expected, observed/expected ratio (o/e) 0.96, 90% interval 0.87 to 1.07. Synonymous variants: 99 observed, 103.75 expected, observed/expected ratio (o/e) 0.95, 90% interval 0.81 to 1.13.
Homologues: Orthologues: chimpanzee LGALS3 (98% identical), macaque LGALS3 (94% identical), dog LGALS3 (86% identical), pig LGALS3 (85% identical), mouse Lgals3 (84% identical), rat Lgals3 (82% identical), rabbit LGALS3 (79% identical), guinea pig LGALS3 (74% identical), tropical clawed frog lgals3 (50% identical), zebrafish lgals3a (44% identical), Caenorhabditis elegans F40H6.5 (28% identical), Caenorhabditis elegans lec-3 (24% identical), and 5 more. Paralogues in human: LGALS9 (32% identical), LGALS9B (32% identical), LGALS9C (32% identical), LGALS4 (28% identical), LGALS8 (25% identical), LGALS12 (20% identical), LGALS7 (17% identical), LGALS7B (17% identical), LGALSL (17% identical), LGALS13 (16% identical), LGALS14 (16% identical), LGALS1 (15% identical), and 4 more.
Diseases named in the same sentence as LGALS3 in open-access papers:
LGALS3 is named in the same sentence as 787 diseases in open-access papers, as found by Europe PMC text mining. Sharing a sentence is not in itself a finding about the gene and the disease. The quoted sentences say what the papers report.
heart failure (340 papers, 2011 to 2026). Inability of the heart to pump blood at an adequate rate to meet tissue metabolic requirements. "Among individuals diagnosed with heart failure and preserved ejection fraction (HFpEF), galectin-3 levels are positively linked to several factors, such as age, creatinine clearance, arterial stiffness, aldosterone, and B-type natriuretic peptide (BNP) levels." (PMID 39129285, 2025). "Large-scale population studies, such as the Framingham Heart Study and PREVEND, have established galectin-3 (gal-3) as a biomarker associated with an elevated risk of heart failure (HF), cardiovascular mortality, and all-cause mortality." (PMID 40699731, 2025). "As a biomarker, elevated circulating galectin-3 predicts major adverse cardiovascular events, heart failure, and mortality, improving risk stratification in multi-marker panels." (PMID 41488050, 2025). "Galectin-3 (Gal-3): Gal-3, a carbohydrate-binding protein, is associated with elevated risk of cardiovascular mortality and heart failure." (PMID 40001586, 2025). "Several studies have shown that galectin-3 is associated with the severity of heart failure, and it has important prognostic information in patients with heart failure." (PMID 40747494, 2025). "Their findings emphasized that galectin-3 upregulation is associated with cardiomyocyte stress and adverse cardiac remodeling, contributing to the progression of heart failure." (PMID 39063659, 2024). "Recently, galectin-3 has also been identified as a biomarker of risk stratification and prognosis in heart failure patients." (PMID 39451549, 2024). "Galectin-3 is linked to an elevated risk of heart failure in the broader population, as well as increased rates of cardiovascular and overall mortality." (PMID 39432214, 2024). "Serum galectin-3 correlated also with markers of left ventricular systolic and diastolic dysfunction, also suggesting its possible role in the stratification of heart failure risk among hemodialysis patients." (PMID 38519721, 2024). "Consistent findings link elevated galectin-3 levels to heightened cardiovascular event risk and heart failure incidence, underscoring its diagnostic potential." (PMID 39063659, 2024). "Galectin-3 (Gal-3), which is a beta-galactoside-binding lectin implicated in fibrosis and inflammation, plays a critical role in the progression of heart failure and kidney injury." (PMID 39057622, 2024). "This study aimed to explore the prognostic value of galectin-3 (Gal-3), a soluble marker associated with fibrosis, inflammation, heart failure, and kidney injury, in patients with cardiac AL amyloidosis." (PMID 39057622, 2024). "A recent meta-analysis also observed a statistically significant association between elevated galectin 3 levels and risk of heart failure." (PMID 38541144, 2024). "In the CARE-HF trial, elevated galectin-3 levels were significantly associated with long-term cardiovascular outcomes in patients with heart failure, left ventricular dysfunction, and dyssynchrony, highlighting its role in fibrosis and adverse remodeling." (PMID 39063659, 2024). "A recent meta-analysis confirmed the association of galectin-3 with long-term all-cause mortality and hospitalization in heart failure patients, cementing its role as a significant prognostic marker." (PMID 39063659, 2024). "Galectin-3, a member of the galectin family, was shown to be of both diagnostic and prognostic value in heart failure patients." (PMID 38248885, 2024). "In individuals at risk of heart failure, elevated markers of type I collagen synthesis, including galectin-3, were correlated with impaired cardiac mechanics, suggesting a potential link between fibrosis and diastolic dysfunction." (PMID 39063659, 2024). "In elderly patients, biomarker profiling indicated that elevated galectin-3 levels were linked to the risk of developing HFpEF, suggesting a predictive value for future heart failure events." (PMID 39063659, 2024).
heart failure (continued). "Galectin-3, a member of the lectin family, has shown significant potential in understanding cardiac fibrosis and remodeling, conditions closely linked to heart failure and adverse cardiac events." (PMID 39767755, 2024). "Galectin-3 has been presented in the literature as a novel biomarker for cardiac disease diagnosis, and a recent meta-analysis has shown that levels of circulating galectin-3 are associated with incident heart failure." (PMID 36959138, 2023). "Galectin-3 can be expressed not only after device implantation but also in various underlying chronic conditions, such as heart failure, chronic obstructive pulmonary disease (COPD), and chronic kidney injury (CKI)." (PMID 38069127, 2023). "It was discovered that higher levels of galectin-3 were linked to an increased risk of heart failure, cardiovascular events, and mortality, indicating its potential as a prognostic marker." (PMID 37602073, 2023). "Galectin-3 is a macrophage lectin product that plays a role in a cascade of events leading to tissue fibrosis which is a hallmark of cardiac remodeling and heart failure." (PMID 37840653, 2023). "Data from the HF-ACTION study on 895 patients with heart failure also showed quite similar results to our study in terms of the association between galectin-3 and age, history of coronary heart disease, BMI, and NT-proBNP (p < 0.05)." (PMID 36673621, 2023). "In another population-based cohort, galectin-3 was associated with all-cause mortality (HR: 1.12, p < 0.001), cardiac death (HR: 1.15, p = 0.033), and heart failure (HR: 1.10, p = 0.049)." (PMID 38132656, 2023). "When modeled as a continuous variable, 1 log unit increase of TNF-α, KIM-1, troponin, and galectin-3 was associated with higher risk of all-cause mortality, cardiovascular death, or subsequent heart failure hospitalization in univariable analysis." (PMID 36896709, 2023). "High galectin-3 levels were associated with the short-term and long-term development of adverse cardiovascular events, heart failure, and re-hospitalization." (PMID 36836225, 2023). "Galectin-3 (Gal-3) is an inflammatory marker associated with the development and progression of heart failure (HF)." (PMID 35463785, 2022). "Galectin-3 and S100/Calgranulin high plasma levels are associated with heart failure, cardiac fibrosis and atherosclerosis." (PMID 36547420, 2022). "Aprevious study of 1342 patients with myocardial infarction found those withhigher galectin-3 levels to have a higher risk of developing heart failure afterMI." (PMID 39077714, 2022). "Clinically, serum galectin-3 levels are significantly increased in patients with heart failure and are often associated with a greater risk of adverse cardiovascular events." (PMID 35042522, 2022). "Adding galectin-3 to the panel of biomarkers assessed in adult patients with heart failure seems to be of great value in predicting the risk of mortality in this cohort." (PMID 35410028, 2022). "The predictive value of galectin-3 for cardiovascular mortality and all-cause mortality in heart failure patients are well established." (PMID 35685493, 2022). "Similar finding was reported by Shah at al., where higher levels of galectin-3 showed clear associations with the Doppler indices of impaired myocardial relaxation and higher filling pressure in patients with heart failure." (PMID 35042522, 2022). "High levels of this biomarker were associated with left ventricular remodeling and mortality in several studies, and a previous study demonstrated an association between galectin-3 concentration and future occurrence of clinically manifest heart failure." (PMID 35087624, 2022). "Significantly, plasma Galectin-3 levels are a prognostic factor for heart failure and were associated with long-term mortality in CCC." (PMID 34867990, 2021). "Elevated galectin-3 level was associated with the development of heart failure in hypertension patients." (PMID 35141299, 2021).
heart failure (continued). "Recently, associations between the biomarker galectin-3 and numerous pathological processes involved in heart failure (HF) and right ventricular (RV) function have been observed." (PMID 34725435, 2021). "There are prior reports on the diagnostic capacity of galectin-3 for heart failure, although most of these involved comparisons with BNP and other indicators." (PMID 35141299, 2021). "The use of sST2 and galectin-3 as prognostic biomarkers was recommended in the 2017 American College of Cardiology/American Heart Association/Heart Failure Society of America HF guidelines." (PMID 35096995, 2021). "In our study, the diagnostic value of galectin-3 was compared with the current “gold standard” for heart function diagnosis in accordance with the latest heart failure diagnostic guidelines." (PMID 35141299, 2021). "In diagnostics of heart failure, NT-proBNP represents the gold-standard laboratory parameter, but also galectin-3 revealed promising results regarding an association with the presence of cardiac dysfunction." (PMID 34561496, 2021). "Pharmacological inhibition of galectin-3 with N-acetyllactosamine (N-Lac) prevented left ventricular dysfunction in heart-failure-susceptible REN2 rats and also demonstrated a protective effect against hypertensive nephropathy in REN2 rats." (PMID 35053194, 2021). "Currently, galectin-3 is a valuable marker for the diagnosis of heart failure that precisely predicts increased risk for mortality during mid-term follow-up." (PMID 33801193, 2021). "Another study found that the risk of heart failure increased by 28% for each SD increase in galectin-3 concentration." (PMID 35141299, 2021). "The area under the curve of galectin-3 was 0.763, indicating that galectin-3 has moderate diagnostic value for heart failure with preserved ejection fraction." (PMID 35141299, 2021). "The increased galectin-3 concentration is associated with the severity of heart failure and can be reduced by spironolactone treatment." (PMID 33513858, 2021). "Binary logistic regression analysis showed that higher galectin-3 concentration was associated with the occurrence of heart failure with preserved ejection fraction." (PMID 35141299, 2021). "In a model in which the risk factors were adjusted, the highest risks of death due to all-causes and cardiovascular death in patients with heart failure were observed when both B-type brain natriuretic peptide and galectin-3 were elevated." (PMID 33195327, 2020). "Galectin-3 has been introduced as another prognostic biomarker for increased mortality risk in heart failure." (PMID 33024450, 2020). "Some studies proved that increased galectin-3 concentration is associated with high heart failure risk." (PMID 33076422, 2020). "It has been well-established that a high concentration of galectin-3 is independently associated with all-cause and cardiovascular mortality and an increased risk of heart failure in the general population." (PMID 33195327, 2020). "Increased levels of circulating galectin-3 have been found in the blood of patients with heart failure and individuals with cardiac hypertrophy, caused by aortic stenosis." (PMID 32119722, 2020). "Galectin-3 is added to the growing list of prognostic biomarkers of heart failure negatively associated with anxiety." (PMID 33024450, 2020). "Galectin-3 is now considered one of the prognostic markers of heart failure and death from cardiovascular causes." (PMID 32119722, 2020). "In clinical routine, Galectin-3 can be used to improve risk stratification in heart failure patients, and its predictive value for adverse cardiovascular events has also been demonstrated in non-heart failure patients." (PMID 32392260, 2020). "In preclinical setting, the infusion of galectin-3 in the pericardial sac of normal animals was associated with the development of significant myocardial fibrosis, cardiac remodeling, and subsequent heart failure." (PMID 31885743, 2019).